GNMT (glycine N-methyltransferase)
Diseases named in the same sentence as GNMT in open-access papers (continued):
Sharing a sentence is not in itself a finding about the gene and the disease.
cancer (22 papers, 2013 to 2025). A tumor composed of atypical neoplastic, often pleomorphic cells that invade other tissues. "Sardh and GNMT are pivotal enzymes associated with sarcosine metabolism, and transcription and protein levels are regulated in cancer tissues." (PMID 33995034, 2021). "Our study offers a mechanism for the effects of GNMT on cancer cells, which is catalysis-independent but associated with nuclear localization of the protein." (PMID 23936142, 2013). "Thus, elevated GNMT in Ames dwarf mice might depress age-associated methylation of CpG islands, perhaps contributing to delayed cancer incidence." (PMID 28351383, 2017). "GNMT has also exhibited an antiproliferative effect in cancer cells, and it is characterized as a key protein in modulating the SAM/SAH ratio to prevent aberrant methylation." (PMID 37047834, 2023). "GNMT exerts, at molecular level, a multifaceted suppressive action by interacting with various cancer-related genes and inhibiting their expression." (PMID 36676960, 2022). "Similar to ALDH1L1, GNMT is highly expressed in the liver (comprising up to 3% of the total cytosolic protein in hepatocytes) but ubiquitously downregulated in many cancers, including HCC." (PMID 34203215, 2021). "GNMT is expressed at a low level in the majority of cancer cell lines and produces an antiproliferative effect, though to a lesser extent than does ALDH1L1." (PMID 34203215, 2021). "At the same time, a transient expression of GNMT in non-cancer origin HEK293 cells (immortalized human embryonic kidney cell line) did not produce noticeable effects on proliferation." (PMID 23936142, 2013). "In the present study, we have investigated the effect of GNMT, a folate regulatory enzyme, on cancer cells." (PMID 23936142, 2013). "The MTT assay has further shown that GNMT expression induced strong antiproliferative effects in all three studied cancer cell lines." (PMID 23936142, 2013). "The present study indicated that restoring MAT1A and GNMT expression may suppress EEF1D expression that is potentially oncogenic in human cancer progression." (PMID 35008908, 2022). "GNMT therefore has a protective role in cellular defense against DNA damage and human cancer." (PMID 35008908, 2022). "Our study indicated that restoring MAT1A and GNMT expression may suppress EEF1D expression that is potentially oncogenic in human cancer progression." (PMID 35008908, 2022). "This is the first study demonstrated that MAT1A and GNMT, the 2 key enzymes involved in methionine cycle, could potentially attenuate cancer progression via suppression of ribosome translation." (PMID 35008908, 2022). "The strong stimulation of GNMT by androgen together with the detection of its expression in AR-positive cancer cell lines and its inhibition upon AR knockdown indicated that AR may directly regulate GNMT expression." (PMID 23997240, 2013). "Importantly, GNMT, a predominantly cytoplasmic protein, was translocated into nuclei upon transfection of cancer cells." (PMID 23936142, 2013). "In the present study, we observed that GNMT is strongly down regulated in human cancers and is undetectable in cancer cell lines while the transient expression of the protein in cancer cells induces apoptosis and results in the activation of ERK1/2 as an early pro-survival response." (PMID 23936142, 2013). "Thus, the overall relationship between GNMT and cancer is reminiscent of another folate regulatory enzyme, ALDH1L1, which is also silenced in tumors and exerts strong antiproliferative effects in cell culture models." (PMID 23936142, 2013). "Furthermore, we have shown for the first time that GNMT exerts a direct inhibitory effect on cancer cells by inducing apoptosis." (PMID 23936142, 2013). "Therefore, down regulation of GNMT in cancers could be explained by the necessity to support high levels of SAM." (PMID 23936142, 2013).
cancer (continued). "The exchange of this oncomiR through exosomes, between cancer cells, can contribute to cancer proliferation by targeting the glycine N-methyltransferase (GNMT), an oncosuppressor gene with multiple roles in preventing cancer." (PMID 32235370, 2020). "Other genes involved in one-carbon metabolism were found transcriptionally repressed in HCC tissue, although the methylation pattern was unchanged in BHMT1, BHMT2, CBS, GNMT, and MTHFD2L in cancer as compared to cancer-free tissue or decreased in FOLH1." (PMID 25945129, 2015). "To further corroborate these findings, we interrogated the RNA-seq data from the Cancer Cell Line Encyclopedia (CCLE) database and observed that SARDH, PIPOX, and GNMT, which are responsible for the conversion between glycine and sarcosine, were scarcely expressed in commonly used LUAD cell lines." (PMID 40275333, 2025). "In contrast, RT4 cells derived from non-invasive cancers expressed low GNMT, and SAM treatment did not produce sarcosine and did not promote malignant phenotypes." (PMID 38003554, 2023). "As a consequence, GNMT inhibits bronchopulmonary dysplasia that follows oxidative stress, inflammation and fibrosis induced by PARP1, and the role of NFKB in inflammation, immune response, and cancer." (PMID 36676960, 2022). "In contrast to ALDH1L1, GNMT, another folate-related enzyme commonly silenced in human cancers, was not expressed in NIH3T3 cells." (PMID 29979702, 2018). "Further studies needed to elucidate this non-genomic effect of androgens and its relationship with GNMT-related pathogenesis of cancer." (PMID 23883094, 2013). "GNMT exerts the suppressor effect primarily in cells originated from malignant tumors: transformed cell line of non-cancer origin, HEK293, was insensitive to GNMT." (PMID 23936142, 2013).
infection (2 papers, 2018). The state of being infected such as from the introduction of a foreign agent such as serum, vaccine, antigenic substance or organism. "For the GNMT genes, expression levels in the infected group were significantly higher than those in the control group at 5 and 7 days post-infection and slightly lower than the control group at the first and the last days (1 and 9 days post-infection)." (PMID 29642440, 2018).
GNMT also shares sentences with these, for which no sentence is quoted: chronic hepatitis (6 papers); citrin deficiency (3); fibrosis (3); colitis (2); acute kidney injury (1); alcoholic steatohepatitis (1); aristolochic acid nephropathy (1); benign prostatic hyperplasia (1); cardiomyopathy (1); cardiovascular disease (1); cerebrovascular disease (1); Cholestatic liver disease (1); cognitive decline (1); genetic diseases (1); glaucoma (1); Glucose intolerance (1); heart failure (1); Hypercholesterolemia (1); ischemic stroke (1); kidney (1); lymph node metastasis (1); melanoma (1); metabolic disorders (1); nonalcoholic steatohepatitis (1); oropharyngeal cancers (1); pancreatic ductal adenocarcinoma (1); schizophrenia (1); Splenomegaly (1); Stroke (1); ulcerative colitis (1).